RN7SL806P (RNA, 7SL, cytoplasmic 806, pseudogene)
Gene: Miscellaneous RNA gene on chromosome 8 (42,881,236 to 42,881,517, forward strand). Ensembl gene ENSG00000242719.
Homologues: Orthologues: chimpanzee Metazoa_SRP (96% identical), macaque Metazoa_SRP (82% identical). Paralogues in human: RN7SL296P (76% identical), RN7SL2 (75% identical), RN7SL1 (75% identical), RN7SL122P (74% identical), RN7SL3 (74% identical), RN7SL219P (73% identical), RN7SL851P (73% identical), RN7SL220P (73% identical), RN7SL680P (73% identical), RN7SL597P (72% identical), RN7SL5P (72% identical), RN7SL753P (72% identical), and 700 more.